MYD88 (MYD88 innate immune signal transduction adaptor)
Diseases named in the same sentence as MYD88 in open-access papers (continued):
Sharing a sentence is not in itself a finding about the gene and the disease.
Sepsis (continued). "Both allele and genotype distributions of the other 14 SNPs in TLR2, TLR4, TLR9, MyD88, and TOLLIP did not vary significantly between sepsis patients and healthy controls." (PMID 21219635, 2011). "Thus in AMs from diabetic rats with sepsis, the enhanced expression of the molecular brake SOCS-1 decreases MyD88 expression and therefore NFκB activation does not occur." (PMID 23024779, 2012). "To determine whether the absence of TLR2, TLR4 and MyD88 affects the mortality in AKI induced by CLP, we evaluated the survival of all mice for 192 hours after the induction of sepsis." (PMID 22655058, 2012).
viral infection (110 papers, 2008 to 2026). "The TLR4/MyD88/NF-κB axis has been widely implicated in myocardial inflammation across various conditions, including viral infections." (PMID 41472298, 2025). "There was a significant upregulation in the genes responsible for controlling viral infection in both the samples, including interferon-stimulated genes and innate immune-signaling genes associated with MyD88- and RIG-I -like receptors." (PMID 38932113, 2024). "In many viral infections, the upregulation of MyD88 is associated with a decreased antiviral type I IFN response; however, MyD88-deficient mice have shown an increased type I IFN response and survivability." (PMID 39125989, 2024). "Especially, we need to enroll more patients with other types of virus infection to validate the diagnostic value of lnc-MyD88." (PMID 36793272, 2023). "In TLR7-deficient mice, viral infection still induced the mRNA expression level of MyD88 and NF-κB but they were lower than those in wild type mice." (PMID 37089926, 2023). "The increased susceptibility and high mortality of viral infections has been noted in MyD88−/− and TLR3−/− knockout mice at the early stage of infection." (PMID 32824595, 2020). "On one hand MyD88 signalling is required to limit the bacterial burden and mice with a Myd88-deficiency have increased susceptibility to bacterial and viral infections." (PMID 29247242, 2017). "Similar mechanisms likely contribute to protect MyD88- or IRAK4-deficient patients from viral infections." (PMID 25954804, 2015). "Since B cells, CD4+ T cells, and DCs are all known to regulate antibody responses, it is possible that an increased level of viral infection of one of these cell types during the acute phase was responsible for the antibody defect in Myd88-deficient mice." (PMID 19214214, 2009). "Though MyD88 mediated proinflammatory signaling has been implicated in the protection from numerous bacteria and parasitic infections, few in vivo studies have implicated MyD88 in protection from viral diseases." (PMID 19079579, 2008). "During systemic MCMV infection, MyD88-deficient mice were more resistant to viral infection than Ifnar1-KO mice, showing that other cell types contributed to IFN-I-dependent antiviral defense in the absence of pDCs, consistent with the STING-dependent contribution of stromal cells to this function." (PMID 38777879, 2024). "It has also been reported that with many virus infections, upregulation of MyD88 is associated with the impairment type IFN response, and MyD88 inhibition improved type IFN response and suppressed virus replication and improved survival in a mouse model of multiple viral diseases." (PMID 33834387, 2021). "Furthermore, recent reports also describe that MyD88 upregulation with many viral infections is linked to decreased antiviral type I IFN response, and MyD88-deficient mice showed an increase in survivability." (PMID 33834387, 2021). "During viral infection, MyD88 recruits members of the interleukin-1 receptor-associated kinase (IRAK)-1 and/or -4 to activate transcription factors belonging to the NF-κB and activator protein 1 (AP-1) family via TRAF6 and transforming growth factor beta-activated kinase 1 (TAK1)." (PMID 29789500, 2018). "Galindo and his co-workers showed that colonization by commensal microbes in newly hatched zebrafish primes neutrophils and induces several genes encoding pro-inflammatory and antiviral mediators via TLR/MyD88 signaling pathway, which increased the resistance of larva to viral infection." (PMID 30233415, 2018). "Also, recent research revealed underlying mechanisms of MyD88 in the impairment of antiviral type IFN signaling through MyD88-IRF interaction which influences MyD88-independent alternate pathways of immune signaling with many virus infections." (PMID 33834387, 2021). "Moreover, it is unknown whether other immune responses could compensate for MyD88 deficiency during resistance to viral infections in mice as must occur in humans." (PMID 25954804, 2015).
viral infection (continued). "Importantly, Myd88 deficiency may increase susceptibility to in vivo parasitic, bacterial, and viral infections, as well as alter normal inflammatory responses." (PMID 21557220, 2011). "These Gal3 inhibitors and MyD88 inhibitors can be used separately as standalone drugs or in combination to obtain optimal results against viral infections, including SARS-CoV-2." (PMID 39125989, 2024). "TLR3 has been identified as the major MyD88-independent PRR stimulated in the type-1 IFN responses to many different viral infections due to its intracellular localization." (PMID 38172683, 2024). "During viral infection, MyD88 is upregulated, and the interaction of MyD88 through its TIR domain with IRF-3/IRF-7 sequesters IRF-3/IRF-7." (PMID 39125989, 2024). "For instance, a recent study indicated that virus infection activates Sox4 expression and its binding to the promoter of the MyD88 gene, resulting in the inhibition of MyD88 transcription." (PMID 38891876, 2024). "In order to further elucidate the effect of HST on the viral infection outcome in rare minnows, the mRNA levels of Hsp70, IL-1β, MyD88 and NF-κB in rare minnows were systematically monitored following GCRV challenge at Day 0, 2, 4, 6, 8 and 10 p.i.." (PMID 38932213, 2024). "Our data have demonstrated that MyD88 or IFNAR1 KO mice are highly resistant to lethal the Delta P80 virus infection compared with WT mice." (PMID 39652608, 2024). "Further, MyD88 KO mice, which were resistant to the Delta P80 virus infection, exacerbated the disease after intranasal administration of IFN-α/β at 2 days post infection." (PMID 39652608, 2024). "In many viral infections, the upregulation of MyD88 impaired the type I IFN response, and the inhibition of MyD88 improved the type I IFN response, suppressed viral replication, and improved animal survival." (PMID 39125989, 2024). "MyD88 dimer formation and its recruitment to the signaling cascade lead to the upregulation of NF-κB-mediated pro-inflammatory cytokines during viral infection." (PMID 39125989, 2024). "Meanwhile, TLRs recruit either TIR domain-containing adaptor inducing IFN-β (TRIF) adaptor protein or myeloid differentiation primary response 88 (MyD88) to transmit signals from viral infections." (PMID 37928266, 2023). "Taken together, the outcomes of these studies show that inhibition of MyD88 by 4210 can amplify IFN production during viral infections and stands as another example of targeting host proteins to intervene in alphavirus infection." (PMID 36851628, 2023). "Several kinases, such as p38, ERK, AP-1, and MKK4/7, were mapped to the TLR/MyD88-dependent pathway, which is known to regulate the host innate immune responses to viral infection." (PMID 35563518, 2022). "We term such newly observed facts as “cytokine-storm” in the (B) treatment that compared septic KO MyD88 mice with untreated wildtype mice, similar to that in viral infections." (PMID 35774781, 2022). "Saikh describe that MyD88 up-regulation with many viral infections is linked to decreased antiviral type I IFN response, and MyD88 exert an inhibitory effect on the TRIF-mediated downstream signaling pathway of the type I IFN response." (PMID 35408954, 2022). "Unexpectedly, we found that IL-18 signaling is dispensable during viral infection in vivo, while the upregulation of nutrient transporters is primarily MyD88-dependent." (PMID 34093543, 2021). "Basically, these reports suggest that MyD88 upregulation impairs the type I IFN response during many virus infections." (PMID 33834387, 2021). "Viral infections or agonists of TLR7 or TLR9 can activate IRF5 in DCs in vitro in a MyD88-dependent manner." (PMID 31999809, 2020). "The importance of the adaptor proteins TRIF, RIG-I, TBK1 and MyD88 in the pathogenesis of viral infections has been well established." (PMID 33335135, 2020).
viral infection (continued). "The signaling adaptor MyD88 has been demonstrated to activate IRF-7 for induction of type I IFN by pDCs in response to virus infection and TLR7/9 activation." (PMID 32373120, 2020). "MyD88 was targeted by miR-7 and miR-21 during several viruses infection enabling these viruses to evade the immune surveillance system to enhance their proliferation." (PMID 32019511, 2020). "NLRP3 and MyD88 are primary activators of cytokine storm in human cells in response to pro-inflammatory stimuli, as well as bacterial and viral infection." (PMID 33096896, 2020). "On the contrary, studies have provided evidence regarding the protection provided by the TLR3 and MyD88-dependent signaling pathways against viral infections." (PMID 32824595, 2020). "Myeloid differentiation protein 88 (MyD88) is critical for the development of innate and adaptive immunity during virus infection." (PMID 31330869, 2019). "For example, the activation of Toll-like receptor 3 (TLR3) during viral infection leads to the downregulation of DISC1 through myeloid differentiation primary response gene 88 (MYD88) and subsequently impairs dendritic arborization and neuronal development." (PMID 30285728, 2018). "Viral infections can activate innate immune signaling within the heart through Myd88-dependent (TLR7–9) and MyD88-independent pathways (TLR3)." (PMID 29077004, 2017). "It was demonstrated that MyD88 played an important role in defense against viral infection and subsequent tissue repair." (PMID 27294155, 2016). "In contrast, intrinsic MyD88 was required to sustain proliferation of effector Tc1 cells in a model of protracted viral infection." (PMID 26367276, 2015). "During viral infections in mice, the impact of MyD88 inactivation or pDC depletion had only been assessed on the basis of IFN-I production." (PMID 25954804, 2015). "For example, MyD88 activation in the presence of viral infection can decrease Polypyrimidine Tract Binding Protein (PTB) mRNA levels (although PTB mRNA levels are not affected by LPS stimulation in our RNAseq data)." (PMID 25658809, 2015). "On the other hand, while patients genetically deficient for MYD88 or IRAK4 show enhanced susceptibility to mycobacteria, they are resistant to most viral infections." (PMID 25954804, 2015). "Our study demonstrates that even undetectably low levels of IFN-I/III are sufficient to induce a strong and widespread expression of genes involved in cell-intrinsic antiviral immunity during a systemic viral infection, including in MyD88-/- mice." (PMID 25954804, 2015). "P38 MAPK is a determinant of virus infection, which depends on MyD88 expression and Toll-like receptor 4 (TLR4) ligation, and the inhibition of p38 MAPK signaling significantly inhibits virus replication." (PMID 23731466, 2013). "Collectively, our results suggest that innate sensing of viral infection results in a MyD88-dependent induction of chemotactic factors that induce the recruitment of neutrophils." (PMID 22496659, 2012). "TRIF-dependent pathway (MyD88-independent pathway) is more involved in generating a type I IFN-dependent response that is essential to host defence against viral infection." (PMID 22144896, 2011). "The induction of TLR3 (recognizing dsRNA) and TLR7 (recognizing ssRNA) suggests enhanced vigilance against viral infection activated by type I IFNs (MYD88 was also up-regulated)." (PMID 20339534, 2010). "To assess lung damage and pulmonary inflammation throughout the course of virus infection in WT and MyD88−/− mice, we evaluated hematoxylin and eosin stained lung tissue sections from 2, 4 and 6 dpi." (PMID 19079579, 2008). "The role of MyD88 in the host response to viral infection has been investigated for a number of viral pathogens." (PMID 19079579, 2008).
viral infection (continued). "When the viral ssRNA is detected, TLRs, in conjunction with the MyD88 protein—an essential and universal adapter in viral infections that mediates signal transduction for all TLRs —along with RIG-I-like receptors (RLRs) in the cytoplasm, trigger a signaling cascade." (PMID 40906234, 2025). "More recent data also show that patients with inherited MyD88 or IRAK-4 deficiency are at increased risk of severe hypoxemic COVID-19 pneumonia, underlining the need for close monitoring and aggressive supportive care during viral infections." (PMID 41369391, 2025). "For instance, upregulation of MyD88 during many virus infections is associated with a decrease in antiviral type I IFN induction, and research indicates that the MyD88 inhibitor compound 4210 exhibits broad-spectrum antiviral activity by upregulating type I interferon." (PMID 41011811, 2025). "Overall, these data suggest that, during viral infection, targeting MyD88 inhibition may facilitate an increased IFN response." (PMID 39125989, 2024). "During a viral infection, after binding viral PAMPs, activated TLRs use two main adaptor molecules to transduce received signals: the Myeloid differentiation primary response 88 (MyD88) and the TIR domain-containing adapter-inducing interferon-β (TRIF) protein." (PMID 38390874, 2024). "Recent studies have demonstrated that MYD88 upregulation during many viral infections impaired host antiviral type I IFN response, and its dysregulation/over-activation contribute to exacerbated inflammatory response, the so-called cytokine storm, in many virus diseases." (PMID 39408741, 2024). "Interestingly, MyD88 KO mice exhibited resistance to lethal infection with the Delta P80 virus infection." (PMID 39652608, 2024). "In addition, MyD88 KO mice, which were resistant to the Delta P80 virus infection, exacerbated the disease after intranasal administration of TNF-α at 2 days p.i.." (PMID 39652608, 2024). "However, the mRNA and protein expression levels of MyD88 and NF-κB p65 in the lung tissues of TLR7-deficient mice infected with FM1 were similar between the forsythiaside A treatment group and the viral infection group." (PMID 37089926, 2023). "Moreover, the mRNA and protein expression levels of TLR7, MyD88, and NF-κB p65 in the lungs of mice were significantly increased after viral infection but significantly downregulated in berberine treatment group." (PMID 37089926, 2023). "In addition, MyD88 mediates IL-1 and IL-18 signaling downstream of the IL-1 receptor and inflammasome signaling plays a role in early containment of the viral infection." (PMID 35464475, 2022). "Thus, TLR4 appears to have 2 pathway arms whose balance is dysregulated in viral infections: one predominantly proinflammatory that exacerbates myocarditis (MyD88 dependent) and the other anti-inflammatory and anti-viral (MyD88 independent)." (PMID 33505220, 2021). "Since previous reports suggest TLR2 or 4 is in charge of viral infection we presumed that spore might trigger MyD88 signaling upon direct engagement with TLRs on AM." (PMID 30930867, 2019). "Following viral infection, TLRs predominantly employ either of two pathways: the MyD88-dependent pathway or the TRIF-dependent pathway, via different TIR-domain containing adaptor proteins, such as MyD88, Mal (MyD88 adaptor-like protein), TIRAP (TIR-associated protein), TRIF and TRAM." (PMID 29558453, 2018). "In view of the putative role of viral infection in pathogenesis of SMZL and recent finding of activating mutations in MYD88 (an adaptor in TLR signalling) in SMZL, we investigated whether IRF5 was targeted by mutation." (PMID 23028731, 2012). "The study of MyD88−/− mice has allowed to demonstrate a crucial role of this molecule for pDC IFN-I production in response to in vitro stimulations by virus type stimuli as well as in vivo during viral infections." (PMID 21994554, 2009).